MIR6511A3 (microRNA 6511a-3)
Synonyms: hsa-mir-6511a-3; MIR6511A-3
Gene: MicroRNA gene on chromosome 16 (16,368,876 to 16,368,942, forward strand). Ensembl gene ENSG00000276311.
Homologues: Paralogues in human: MIR6511A1 (100% identical), MIR6511A2 (100% identical), MIR6511A4 (100% identical).